ARAF (A-Raf proto-oncogene, serine/threonine kinase)
Diseases named in the same sentence as ARAF in open-access papers (continued):
Sharing a sentence is not in itself a finding about the gene and the disease.
ARAF also shares sentences with these, for which no sentence is quoted: infection (31 papers); Alzheimer disease (4); colon carcinoma (4); cardiovascular diseases (3); hepatocellular carcinoma (3); Noonan syndrome (3); ovarian carcinoma (3); pancreatic cancer (3); adenocarcinoma (2); amyotrophic lateral sclerosis (2); glioblastoma (2); Langerhans cell histiocytosis (2); metastatic melanoma (2); neurodegenerative disease (2); prostate carcinoma (2); schistosomiasis (2); toxoplasmosis (2); adrenoleukodystrophy (1); albinism (1); alcoholism (1); arrhythmogenic right ventricular cardiomyopathy (1); atherosclerosis (1); autoimmune disease (1); bacterial disease (1); cholangiocarcinoma (1); Chylothorax (1); cocaine addiction (1); colorectal cancer (1); diabetes (1); hawkinsinuria (1).
A further 29 diseases each share a sentence with ARAF in 1 paper.